KRT17P3 (keratin 17 pseudogene 3)
Gene: Transcribed unprocessed pseudogene on chromosome 17 (30,567,700 to 30,571,748, reverse strand). Ensembl gene ENSG00000231870.
Diseases named in the same sentence as KRT17P3 in open-access papers:
KRT17P3 is named in the same sentence as 1 disease in open-access papers, as found by Europe PMC text mining. Sharing a sentence is not in itself a finding about the gene and the disease. The quoted sentences say what the papers report.
lung carcinoma (1 paper, 2026). "Previous studies have found that the keratin 17 pseudogene 3 (KRT17P3) is overexpressed in lung cancer tissues from patients who are resistant to cisplatin." (PMID 41362671, 2026).